PGR (progesterone receptor)
Diseases named in the same sentence as PGR in open-access papers (continued):
Sharing a sentence is not in itself a finding about the gene and the disease.
breast cancer (continued). "Since BMI and tumor glucose metabolism are both linked to breast cancer subtypes and patient outcome, the combination of these two prognosticators may have added prognostic value to the tumor subtype according to estrogen receptor, progesterone receptor, and HER2 status." (PMID 27798667, 2016). "Immunostaining for ER and PgR has been reported to be useful for diagnosing metastatic tumors from breast cancer, although 32% and 12% of primary gastric cancer cases are positive for ER and PgR, respectively." (PMID 27957354, 2016). "Estrogen receptor (ER) and progesterone receptor (PR) are the most commonly used biomarkers for breast cancer subtyping." (PMID 27863437, 2016). "Endocrine therapies are an established treatment for postmenopausal women with hormone receptor-positive advanced breast cancer (estrogen receptor [ER]-positive and/or progesterone receptor [PgR]-positive)." (PMID 27359058, 2016). "In a microRNA expression profiling of 20 different breast cancer samples, representing common breast cancer phenotypes, an association with HER2, estrogen (ER) and progesterone receptor (PR) status was shown." (PMID 26821018, 2016). "In fact, there is a broad consensus that breast cancer therapy has become more and more individualized on the basis of pathological molecular markers such as estrogen receptor (ER), progesterone receptor (PR) and HER-238." (PMID 27845412, 2016). "Estrogen receptor (ER) and progesterone receptor (PR) statuses are also well known prognostic and predictive factors and play a key role in breast cancer outcome and treatment." (PMID 27806715, 2016). "In order to gain insight on this distinctive group of patients, we examined the status of the known molecular markers for breast cancers, namely estrogen receptor (ER), progesterone receptor (PR), and HER2." (PMID 27556157, 2016). "Breast cancer subtypes defined by their estrogen receptor (ER), progesterone receptor (PR), or human epidermal growth factor receptor 2 (HER2) status likely arise via different carcinogenic mechanisms." (PMID 27443187, 2016). "This subtype (luminal, ESR1+, PGR+) represents 40-75% of newly diagnosed breast cancers and responds well to hormone therapy." (PMID 26783963, 2016). "Breast cancer prognosis and treatment mostly relies on a few markers such as the estrogen receptor (ER), progesterone receptor (PgR), the human epidermal growth factor receptor 2 (HER2/neu) and tumor stage." (PMID 26870995, 2016). "The independent predictive information from progesterone receptor (PgR) positivity for breast cancer treated with tamoxifen has been questioned after an overview by the Early Breast Cancer Trialists’ Collaborative Group (EBCTCG)." (PMID 27722840, 2016). "We analysed a panel of forty breast cancer samples consisting of 14 oestrogen receptor and/or progesterone receptor positive cases, 15 Her2 positives and 11 TNs." (PMID 26725330, 2016). "This breast cancer subgroup lacks expression of estrogen receptor alpha (ERα) and progesterone receptor (PR) as well as human epidermal growth factor receptor 2 (HER2) amplification." (PMID 28003019, 2016). "Breast cancers are routinely classified by stage, pathology, grade, and by the expression of estrogen receptor (ER), progesterone receptor (PgR), or human epidermal growth factor receptor (Her2/neu)." (PMID 27527135, 2016). "One of the first applications of genomic medicine into breast cancer care in HICs was the identification of estrogen receptor (ER), progesterone receptor (PR), and human epidermal growth factor receptor 2 (HER2) tumor markers to target treatment." (PMID 27413551, 2016). "The intrinsic subtypes of breast cancer were determined by the immunohistochemical expression of ER, PgR, and HER2." (PMID 27334118, 2016). "The aim of this study was to investigate the predictive value of PgR determined by IHC in ER-positive breast cancer." (PMID 27722840, 2016).
breast cancer (continued). "Clinically, breast cancer represents a heterogeneous disease that is mainly grouped based on its hormone receptor (estrogen receptor [ER] or progesterone receptor [PR] positivity) and amplification of the ERBB2 gene (hereafter referred to as HER2+)." (PMID 26835221, 2016). "Several markers have been used in breast cancer diagnosis, including estrogen receptor (ER) and progesterone receptor (PR)." (PMID 27462610, 2016). "In breast cancer, the oncogenic roles of nuclear steroid hormone receptor (HR) signaling mediated by the estrogen receptor (ER) and progesterone receptor (PR), respectively, have been extensively characterized." (PMID 27285752, 2016). "In this study, the expression of PgR in young women was more frequent than in older women with breast cancer (p = 0.01)." (PMID 27760178, 2016). "Although expression of estrogen receptor (ER), progesterone receptor (PR), and cell proliferation marker Ki67 serve as predictive and prognostic factors in breast cancers, little is known about their roles in normal breast tissue." (PMID 28111631, 2016). "Human breast cancers are classified clinically based on their expression of the estrogen receptor (ER), progesterone receptor (PR), and human epidermal growth factor receptor 2 (HER2)." (PMID 27590511, 2016). "Fulvestrant is recommended as one of the treatment choices for postmenopausal patients with hormone-sensitive (ER- and/or PgR-positive) advanced breast cancer by the most recent National Comprehensive Cancer Network Guidelines." (PMID 27359058, 2016). "Because many EDCs are capable of affecting other nuclear receptors, we tested BPAP effects upon modulating the levels of several endogenous NRs (ER, glucocorticoid receptor, GR, and progesterone receptor, PR) in breast cancer cells." (PMID 26918604, 2016). "Histology confirmed metastasis compatible with breast cancer, ER 100% PgR 5%, Ki-67 5% and c-erbB2 0%." (PMID 27556456, 2016). "Two main classes of breast cancer (BC) are distinguished by the expression of hormone receptors (HR); namely oestrogen receptor (ER) and progesterone receptor (PR)." (PMID 27406316, 2016). "Several studies use creatine for calculation of metabolic ratios to allow for comparable quantities between samples and in studies of breast cancer tissue, higher level of this metabolite have been correlated to ER-positive and PgR-positive tumors." (PMID 26858940, 2016). "BRCA-positive patients were significantly younger than sporadic breast cancer patients, and less likely to be ER-, PgR- or c-erbB2-positive than women with BRCA-wild type or sporadic breast cancer." (PMID 27899083, 2016). "PGR gene expression showed lower levels in malignant mammary tumors of neutered dogs compared to intact females in FFPE samples, but not in fresh frozen samples." (PMID 27649560, 2016). "Despite the identification of ERα as the upsteam molecular of H19, we also concerned the expression of ERβ and progesterone receptor (PR) in chemoresistant breast cancer cells." (PMID 27845892, 2016). "In this study we further evaluate the expression of AGO2 across breast cancer tumor samples with different degrees of receptor status (ERα, PGR, and HER2) and tumor molecular subtype." (PMID 29657266, 2016). "The subtype of breast cancer can be divided based on the expression of estrogen receptor (ER), progesterone receptor (PR) and Her2 receptor tyrosine kinase (Her2)." (PMID 26883017, 2016). "There are four subtypes of breast cancer based on the expression of ER, progesterone receptor (PR), or HER2: ER, PR+, HER2+; ER, PR+, HER2–; ER, PR–, HER2+; and ER, PR–, HER2–." (PMID 26716652, 2016). "ER and PGR expression were detected in 15/19 (78.95 %) and 13/19 (68.42 %) of the breast cancer primaries and in 19/34 (55.88 %) and 11/34 (32.35 %) of the liver metastases." (PMID 26862065, 2016). "The actions of ER, Progesterone Receptor (PR), and Androgen Receptor (AR) in mediating breast cancer growth are well described in the literature." (PMID 26300846, 2015).
breast cancer (continued). "Clinically, the breast cancer is classified into several molecular subtypes based on the estrogen receptor (ER), progesterone receptor (PR), human epidermal growth factor receptor-2 (HER2) and Ki-67 index status." (PMID 26600129, 2015). "In particular, breast cancers that overexpress the estrogen receptor (ER), progesterone receptor (PR), and/or human epidermal growth factor 2 receptor (HER2) can be specifically targeted with hormonal and/or anti-HER2 therapies." (PMID 26600392, 2015). "In the present study, we investigated the relationship between PgR expression and long-term survival in Luminal-type breast cancer patients who received NCT, aiming to identify a distinct subset of ER+ tumors." (PMID 26053183, 2015). "The tumor biology of sex steroid hormone receptors, such as the estrogen receptor (ER) and the progesterone receptor (PR), has been studied, especially in breast cancers." (PMID 26318038, 2015). "The estrogen receptor (ER), progesterone receptor (PR), PS-2 (an regulated protein of estrogen) and nm23 (a tumor metastasis inhibitory gene) have been considered good prognostic indicators in breast cancer." (PMID 26472025, 2015). "In summary, ER-/PgR+ tumors are a rare, but defined subgroup of breast cancer occurring more frequently in younger women." (PMID 26161666, 2015). "To further investigate this association, we observed increases in the SIPL1 gene and mRNA in the breast cancer subtypes of estrogen receptor (ER)+, progesterone receptor (PR)+, HER2+, or triple negative." (PMID 25992689, 2015). "We tested each of the six active compounds for its ability to inhibit progestin-stimulated progesterone receptor (PR) activity in a PR+ breast cancer cell line (T47D), using the MMTV-Luc reporter." (PMID 26575173, 2015). "Breast cancer is a heterogeneous disease, with major subtypes defined by expression of estrogen receptor (ER), progesterone receptor (PR) and HER2 receptor." (PMID 26356563, 2015). "Recently, G. Cancello reported a relatively good prognosis in the PgR+ subgroup of Luminal-B patients and highlighted the significant impact of PgR status on the outcome of patients with early breast cancer." (PMID 26053183, 2015). "Six patients had estrogen receptor (ER)-positive breast cancer as assessed by a local laboratory, of whom 4 patients were positive for both ER and progesterone receptor." (PMID 25967286, 2015). "According to the American Society of Clinical Oncology, approximately 60% to 75% of women with breast cancer have estrogen receptor–positive breast cancer and 65% of these cancers are also progesterone receptor (PR) positive." (PMID 26703550, 2015). "This is best highlighted in the breast cancer field, where the proteins estrogen receptor (ER), progesterone receptor (PR), and human epidermal growth factor receptor (HER2) have been well established as prospective treatment response biomarkers." (PMID 25906748, 2015). "In recent years, it has become widely accepted that breast cancer can be classified into multiple subtypes by immunohistochemical (IHC) analysis of the estrogen receptor (ER), progesterone receptor (PgR), HER-2, and Ki-67." (PMID 26053183, 2015). "Molecular profiling has resulted in breast cancer being divided into four main subtypes, defined by differing expression levels of the Estrogen receptor (ER), Progesterone receptor (PR) and growth factor receptor HER2." (PMID 26010605, 2015). "TCPTP protein levels are reduced in a subset of estrogen receptor, progesterone receptor and HER2 triple-negative human breast cancers, and TCPTP deficient breast cancer cell lines exhibit elevated SFK signaling." (PMID 26087188, 2015). "The 129:Stat1-null females develop mammary tumors having a unique ER+, progesterone receptor (PR)+ histological signature distinct from other models." (PMID 26075897, 2015). "Approximately 70% of breast cancer cases express estrogen receptor (ER) and progesterone receptor (PR) thus are referred as hormone receptor (HR)-positive." (PMID 26240785, 2015).
breast cancer (continued). "EZH2 was correlated with histological grade, estrogen receptor expression, and progesterone receptor expression in breast cancer." (PMID 25974088, 2015). "Current clinical management of breast cancer relies on clinicopathological features as well as expression of biological markers such as estrogen receptor (ER), progesterone receptor (PR) and epidermal growth factor receptor 2 (HER2)." (PMID 26142905, 2015). "Tumor biology of estrogen receptor-α (ERα) and progesterone receptor (PR) has been studied in breast cancers." (PMID 26318038, 2015). "Women with estrogen receptor- (ER) and/or progesterone receptor (PR) positive breast cancers are the best candidates for hormone therapy." (PMID 25682200, 2015). "High levels of CAPS were statistically significantly correlated to lower RFS both in uni- and multivariate analyses, including important breast cancer prognostic markers as nodal status, tumor size, age and ER and PgR levels." (PMID 25878567, 2015). "Estrogen and progesterone are important in breast cancers expressing the estrogen receptor (ER) and progesterone receptor (PR)." (PMID 26125438, 2015). "In this study, we have utilized a well-maintained, retrospectively collected dataset of sequential breast cancer patients to explore the clinicopathological characteristics and outcomes of patients with ER-/PgR+ breast cancer." (PMID 26161666, 2015). "The four molecular subtypes of breast cancer possess a number of distinguishing characteristics, including estrogen/progesterone receptor status, response to chemotherapy drugs, and gene expression profile." (PMID 25765044, 2015). "In the case of breast cancer, determining estrogen receptor (ER), progesterone receptor (PR), and human epidermal growth factor receptor 2 (HER2) expression has been routine practice for years." (PMID 26472348, 2015). "The presence of ER is generally agreed to be a favourable prognostic factor, and PgR expression was later shown to add significant prognostic value in breast cancer beyond that obtained with ER alone." (PMID 25938238, 2015). "At the 2013 St Gallen International Breast Cancer Conference, the cut-off point for PgR was increased from 1% to 20% to improve the definition of luminal A breast cancer." (PMID 25938238, 2015). "In the current study, we included four large cohorts of breast cancer cases and systemically studied the clinical features and molecular essence of the ER−/PgR+ phenotype." (PMID 26437901, 2015). "Currently, breast cancer can be subcategorized based on the status (+/−) of the hormone receptors oestrogen receptor (ER) and progesterone receptor (PR) and the Receptor tyrosine-protein kinase erbB-2 (ERBB2 or HER2)." (PMID 25721950, 2015). "It has been reported that MF inhibits proliferation of certain types of hormone-dependent cancers, such as breast cancer positive for the progesterone receptor, ovarian cancer, endometrium cancer, prostate cancer and gastric cancer." (PMID 25622528, 2015). "Here, using a keyword search, we found new clinical data showing that PGR overexpression is a biochemical marker of male breast cancer (T4 tumor) in obesity." (PMID 26694100, 2015). "Breast cancer is a heterogeneous disease, including subtypes based on estrogen receptor (ER) and progesterone receptor (PR) status and amplification of human epidermal growth factor receptor 2 (HER2)." (PMID 26626121, 2015). "Following EMT, trastuzumab resistant PTEN deficient breast cancer cells transform HER2+ cells to a more aggressive TNBC phenotype with reduction in HER2, estrogen, and progesterone receptor expression while increasing proliferation." (PMID 26522776, 2015). "Significant differences in AR expression were observed between the different subtypes of breast cancer, in fact high expression levels of AR were observed in the ER and / or PgR positive one and low in the TN." (PMID 26039245, 2015).
breast cancer (continued). "Compared with ER, PgR is often considered to be a weak prognostic marker for determining breast cancer subtype." (PMID 26053183, 2015). "Clinically, it is generally agreed upon that all newly-diagnosed primary breast cancers should be evaluated for ER and PgR protein expression by immunohistochemistry (IHC)." (PMID 26437901, 2015). "In endometrial cancer cell lines, as well as breast cancer animal models 44,45, metformin has been reported to increase progesterone receptor expression with little effects on ER expression." (PMID 25417601, 2015). "PCYT2 activity has been shown to be increased in breast cancer cells, enabling them to adapt to metabolic stress, and TRERF1 acts as a cell cycle inhibitor in breast cancer cells through the modulation of progesterone receptor." (PMID 26620706, 2015). "Significant discordance in estrogen receptor and progesterone receptor status have been reported between different distant breast cancer metastases within the same patient." (PMID 25730902, 2015). "In another study, 453 miRNAs in 29 early-stage breast cancer tumors were profiled, identifying signatures that accurately predict ER, progesterone receptor (PR), and HER2 status." (PMID 25849621, 2015). "Breast cancers have traditionally been classified on the basis of immunohistochemical reactivity to Estrogen Receptor (ER), Progesterone Receptor (PR) and HER2." (PMID 25679396, 2015). "Luminal-type breast cancer was characterized by profiles of estrogen receptor (ER) positive or progesterone receptor (PR) positive; it showed better prognosis than other subtypes, such as basal-like type and HER2 type." (PMID 25511546, 2015). "Breast cancer subtype, determined by expression of estrogen/progesterone receptor (ER/PR) and human epidermal growth factor receptor (HER)-2, is predictive for prognosis." (PMID 26240784, 2015). "A factor that is seldom addressed in the research of race/ethnicity and SES in breast cancer disparities are the breast cancer tumor markers estrogen receptor (ER), progesterone receptor (PR), and human epidermal growth factor receptor 2 (HER2)." (PMID 26339244, 2015). "In particular, the cell doubling time (CDT) and the expression of the three main prognostic markers of breast cancer, such as ER, PgR and HER2, have been considered." (PMID 26304457, 2015). "This association is also supported by laboratory data that show that PgR expression is more common in breast cancers diagnosed in pre-menopausal women compared to those diagnosed after menopause." (PMID 26161666, 2015). "The stratification of breast cancer patients for endocrine therapies by oestrogen or progesterone receptor expression is effective but imperfect." (PMID 25900183, 2015). "In conclusion, the majority of the ER–/PgR+/HER2– phenotype breast cancer cases are basal-like and a minority is luminal-like." (PMID 26437901, 2015). "Clinically, breast cancers are traditionally classified according to their receptor status, namely estrogen receptor (ER), progesterone receptor (PR), and HER2 (Human Epidermal Growth Factor Receptor 2)." (PMID 26702755, 2015). "First, the majority of breast cancer patients bearing skeletal metastases suffer from estrogen and progesterone receptor-positive cancer." (PMID 25909161, 2015). "Core needle biopsy (CNB) is recommended for an initial breast cancer pathological diagnosis and is used to evaluate estrogen receptor (ER), progesterone receptor (PR), and HER2 status." (PMID 26514283, 2015). "The panelist addressed the “semantic” classification of breast cancer subtypes by pathology-based biomarkers (e.g. estrogen receptor, progesterone receptor and HER2) vs genomic classifiers." (PMID 25932042, 2015). "As a hormone-dependent tumor, ascertainment of estrogen-receptor (ER) and progesterone-receptor (PR) along with HER2 is regarded essential to treatment of breast cancer." (PMID 25956130, 2015).